RNU6-593P (RNA, U6 small nuclear 593, pseudogene)
Gene: Small nuclear RNA gene on chromosome 11 (17,115,652 to 17,115,763, reverse strand). Ensembl gene ENSG00000201586.
Homologues: Orthologues: chimpanzee U6 (98% identical), macaque U6 (90% identical), pig U6 (76% identical), mouse Gm22783 (69% identical), guinea pig U6 (68% identical), rat LOC120099430 (66% identical), guinea pig U6 (62% identical). Paralogues in human: RNU6-1031P (84% identical), RNU6-25P (84% identical), RNU6-29P (84% identical), RNU6-38P (84% identical), RNU6-46P (84% identical), RNU6-1 (83% identical), RNU6-1124P (83% identical), RNU6-1316P (83% identical), RNU6-2 (83% identical), RNU6-20P (83% identical), RNU6-35P (83% identical), RNU6-39P (83% identical), and 1283 more.